MIR451A (microRNA 451a)
Synonyms: hsa-mir-451; MIR451; MIRN451; hsa-mir-451a; mir-451a
Gene: MicroRNA gene on chromosome 17 (28,861,369 to 28,861,440, reverse strand). Ensembl gene ENSG00000284565.
Gene Ontology:
Biological process: miRNA-mediated post-transcriptional gene silencing
Homologues: Orthologues: chimpanzee ptr-mir-451 (100% identical), macaque mml-mir-451 (97% identical), dog MIR451A (92% identical), rat Mir451a (92% identical), pig ssc-mir-451 (81% identical), tropical clawed frog xtr-mir-451 (76% identical), zebrafish dre-mir-451a (68% identical).